CD4 (CD4 molecule)
Diseases named in the same sentence as CD4 in open-access papers (continued):
Sharing a sentence is not in itself a finding about the gene and the disease.
COVID-19 (continued). "This Th1/IL-2-driven profile is frequently associated with effective immunity: in COVID-19, convalescent patients with favorable outcomes exhibit polyfunctional CD4+ T cells secreting IL-2, IFN-γ, and TNF-α, whereas severe cases often show loss of this functionality." (PMID 41357245, 2025). "Lack of T cell responsiveness may be clinically important: impaired CD4+ T cell responses are linked to higher COVID-19 mortality, whereas preserved CD8+ T cells correlate with better outcomes even when antibodies are reduced." (PMID 41011790, 2025). "Additionally, patients with HIV generally have decreased immunological and CD4 counts since the cytokine storm is one of the main mechanisms causing COVID-19-related morbidity and mortality." (PMID 38572011, 2024). "Elevated CD4+ T cell senescence was associated with diminished COVID-19 specific humoral immunity." (PMID 38377029, 2024). "In addition, we used multiple machine learning methods to screen for five risk genes (KLF5, NSUN7, APH1B, GRB10 and CD4), which are used to predict COVID-19 severity." (PMID 38600309, 2024). "Similarly, at D10, we observed a significant association between low CD4+ T cell count and mortality in severe COVID-19 patients." (PMID 38762684, 2024). "In summary, the accumulation of senescent CD4+ T cells may hamper spike-specific antibody production and its neutralizing activity, leading to more severe disease and mortality risk among older COVID-19 patients." (PMID 38377029, 2024). "Activated CD4 T cells contained the greatest number of significant DEGs, further validating the reliability of using the SEACells algorithm for time series analysis given CD4 T cells’ critical involvement in response to SARS-CoV-2 infection." (PMID 38580667, 2024). "Additionally, both the Kaplan-Meier curve and multivariate regression analysis demonstrated that low CD4+ T cell count level (< 156.00 cells/μl) was closely associated with all-cause mortality in COVID-19 patients treated with azvudine." (PMID 39654887, 2024). "In this study, a prominent reduction of CD4+ T cells was found in severe ASyS+COVID cases and a lower CD4/CD8 ratio could serve as a convenient biomarker to identify high-risk ASyS patients with COVID-19." (PMID 38500883, 2024). "We observed this during the critical state of the deceased cases, suggesting that persistent activation of inflammatory CD4 T cells may be associated with decreased survival in COVID-19 patients." (PMID 39530088, 2024). "Immune cell profiling of COVID-19 patients’ blood samples indicated that the diminution of CD4+, CD8+, T, and NK cells could cause lymphopenia." (PMID 38392902, 2024). "The T-cell infectome also exclusively enriched for certain biological pathways, which included apoptotic and necroptotic pathways, supporting a study that saw a decrease in CD4+ T-cell viability after SARS-CoV-2 infection." (PMID 38548777, 2024). "The immune dysregulation that affects the adaptive immune system specifically could play a role in this case, where COVID-19 has been observed to be associated with profound lymphopenia, particularly affecting CD4+ and CD8+ T cells." (PMID 39360101, 2024). "People with PCC were recruited to determine the distribution and functionality of CD4+ T helper (Th) subsets in comparison with individuals with mild, severe, and critical presentations of acute COVID-19 to evaluate their contribution as risk or protective factors for PCC." (PMID 39257580, 2024). "More recently, a low CD4 count has been linked to an impaired response to COVID-19 vaccination." (PMID 38779686, 2024). "This correlation was stronger when analyzing the subgroup of moderate/severe patients (R = −0.596, P = 0.0091), suggesting that in vivo complement activation might be implicated in CD4 lymphopenia observed during acute COVID-19." (PMID 38694513, 2024).
COVID-19 (continued). "While some studies associate HIV with an increased hospitalization or death risks, often linked to factors like low CD4 cell counts and comorbidities, our study found a 12% COVID-19 related mortality rate among PWH, consistent with the average reported across studies (16%)." (PMID 38789972, 2024). "Notably, we demonstrated for the first time the association of PTB and COVID-19 at the single-cell level and identified a causal effect for markers of CD4+ effective memory T cell (CD4+ TEM) cells on PTB and COVID-19." (PMID 39337460, 2024). "Furthermore, multivariate logistic regression analysis also demonstrated a robust association between low CD4+ T cell count (< 156.00 cells/μl) and mortality in COVID-19 patients undergoing azvudine treatment." (PMID 39654887, 2024). "Some authors have found that patients with long COVID-19 present with altered CD4+ and CD8+ T cell populations that could be associated with viral persistence." (PMID 38651389, 2024). "Additionally, the multivariate logistic regression analysis revealed that low CD4+ T cell count (< 156.00 cells/μl) was associated with all-cause mortality in COVID-19 patients treated with azvudine (OR = 5.860, 95% CI = 1.727–19.878, p = 0.005)." (PMID 39654887, 2024). "Our findings present direct experimental evidence for a protective role for seasonal HCoV/SARS-CoV-2 cross-reactive CD4+ T cell responses, consistent with human data implicating cross-reactive CD4+ T cells in protecting against SARS-CoV-2 infection." (PMID 38278784, 2024). "Thus, CD4 T cell responses against the JN.1 variant were reduced in the COVID-19-naïve group, while responses to BA.2.86 and the wild-type proteins remained similar." (PMID 39772110, 2024). "Moreover, strong CD4+ T cell responses have been associated with better clinical outcomes in COVID-19 patients, while reduced levels of CD4+ T cells correlated with higher rates of breakthrough infections or more severe disease." (PMID 39772110, 2024). "While our study focused solely on Th1-associated cytokines, it remains to define whether other Th CD4 subtypes such Th2 or Th17 could as also play a role in COVID-19 protection." (PMID 38235336, 2024). "In conclusion, our findings demonstrate that despite immunosuppression, pSOTRs are capable of mounting humoral and CD4 T+ cell responses to both the ancestral strain and new variants of concern after receiving the primary series and multiple booster doses of mRNA COVID-19 vaccines." (PMID 38580714, 2024). "Further, the severity of COVID-19 could also be due to delayed interferon-gamma response and is associated with a prolonged hyperinflammatory state as well as lower CD4+ and CD8+ cell numbers." (PMID 36839456, 2023). "Among COVID-19– participants, we identified distinct but overlapping repertoire shifts independently associated with natal sex, age, region, cigarette smoking and substance use history, current and nadir CD4, and HIV viremia." (PMID 36805331, 2023). "Moreover, the severity of COVID-19 has been associated with functional CD4+ T-cell abnormalities and CD8+ T-cell fatigue." (PMID 36679947, 2023). "Transplanted engineered clinical-grade MSCs effectively delivered the SARS-CoV-2 antibodies to the lung, and the immune hyperresponsiveness caused by COVID-19 was coordinated by MSC clones through inhibiting the differentiation of CD4 + T cells into Th1 and Th17 subpopulations." (PMID 37653459, 2023). "Indeed, peripheral T cell lymphopenia appeared to be correlated with increased COVID-19 severity, while the COVID-19 recovery is often associated with the occurrence of reactive CD4 and CD8 T cells." (PMID 37316832, 2023). "First, among the COVID-19– participants, different host factors were associated with overlapping but unique humoral repertoire changes — particularly sex, but also age and nadir CD4." (PMID 36805331, 2023).
COVID-19 (continued). "A multicenter study proved that viremia was significantly associated with COVID-19 disease severity and that CD4 a T-cell count < 200 cells/mm3 is not only a factor that leads to increased mortality but also to an increased probability of admission to hospital." (PMID 36851791, 2023). "Previously, it was shown that COVID-19 represents one of the causes eliciting a decline in CD4+ and CD8+ T cells, as well as IFN-γ levels, which may affect lowered diagnostic efficacy for LTBI." (PMID 37626620, 2023). "CD4 T-cell counts are associated with seroconversion in COVID-19-vaccinated PLWH." (PMID 37112701, 2023). "Likewise, an approximately 39 kb Neanderthal haplotype, spanning the MUC20 locus in Eurasians, contains the rs2177336-T allele that increases MUC20 expression in SARS-CoV-2-stimulated cells, particularly for CD4+ T cells, and decreases COVID-19 susceptibility." (PMID 37558883, 2023). "Additionally, severe inflammation in COVID-19 has been linked to the exhaustion of CD4+ T cells, vital for transitioning from inflammation to repair during wound healing." (PMID 38131885, 2023). "However, other studies have shown that when compared to antibodies and CD8+ T-cells, SARS-CoV-2-specific CD4+ T-cells had the strongest association with reduced COVID-19 disease severity." (PMID 37585383, 2023). "People living with HIV, particularly those that are viremic or have low CD4 counts, may be at increased risk of hospitalization and death from COVID-19." (PMID 36851288, 2023). "Mechanisms may include increased lung damage in TB patients with COVID-19, resulting in impaired lung function or higher risk of TB reactivation after COVID-19 infection due to depletion of CD4 T cells and excessive lung fibrosis." (PMID 37841265, 2023). "Autoimmune diseases and inflammatory disorders such as rheumatoid arthritis, systemic lupus erythematosus, and coronavirus disease 2019 (COVID-19) infection can also decrease CD4+CD25+CD127dim+ cells." (PMID 36816803, 2023). "Presented results imply that the underlying mechanism behind increased COVID-19 severity might be overproduction of Th1 and Th17 cytokines by CD4+ Th cells." (PMID 37057213, 2023). "PLWH with low CD4+ count was associated with a higher risk of COVID-19 adverse effects." (PMID 37288215, 2023). "While the antigenic stimulation noted with aging, SARS-CoV-2, and HIV infection was associated with CD4+ T-cell lymphopenia, the lymphopenia associated with aging and COVID-19 occurs mainly within the context of subgrades tracking CD8-CD4 equilibrium (e.g., IHG-IIb and IHG-IIc)." (PMID 37311745, 2023). "Together, these data reveal similar associations of current and nadir CD4 with the non–SARS-CoV-2 repertoire among COVID-19– participants, but they also show a novel association of nadir CD4 with the SARS-CoV-2 repertoire among COVID-19+ participants not seen with current CD4." (PMID 36805331, 2023). "Severe COVID-19 is associated with significantly reduced CD4+ lymphocyte frequency and dysfunction." (PMID 37376562, 2023). "FcγRIII and CD4+ cells are of great importance due to their association with COVID-19 prognosis." (PMID 35930526, 2022). "Evidence now suggests that immune dysregulation in PWH with lower CD4 counts could potentially result in an exaggerated immune response and increased risk of severe COVID-19 by reducing the overall SARS-CoV-2 specific CD4 T cells." (PMID 35725387, 2022). "The dysregulation associated with COVID-19, with the reduction of T lymphocytes, CD4+T, and CD8+T cells, may alter innate immunity." (PMID 36721573, 2022). "Many studies suggested that the immune dysregulation in patients with severe COVID-19, especially CD4+ lymphopenia, may increase the risk of PJP." (PMID 35736068, 2022). "Other studies of blood demonstrated that severe COVID-19 is associated with an increase in IL-6, activated macrophages and neutrophils and a T cell lymphopenia that contribute to lower proportions of antigen-specific CD4+ and CD8+ T cells." (PMID 36211412, 2022).
COVID-19 (continued). "However, other factors such as age, which is associated with a decline in naïve CD4+ Th cell counts, and HLA restrictions, which influence the T cell repertoire developed in response to infection, also influence COVID-19 trajectories." (PMID 35401519, 2022). "Furthermore, the prompt and effective induction of SARS-CoV-2-specific CD4+ T cells and their presence in circulation within 2–4 days post-symptom onset in acute COVID-19 were associated with mild/moderate COVID-19 and good prognosis." (PMID 35337103, 2022). "Consistent with past studies, we found that COVID-19 was associated with an increase in neutrophil frequency and a concomitant decrease in other circulating leukocyte populations including monocytes, basophils and both CD4 and CD8 T cells." (PMID 35421120, 2022). "Recently it was demonstrated that a response from CD4+ T cells might be associated with COVID-19 severity." (PMID 35651623, 2022). "Additionally, CD4+ T-cell responses associated with milder disease in acute and convalescent COVID-19 patients, showing its role in controlling and resolving a primary SARS-CoV-2 infection." (PMID 36032096, 2022). "In particular, this study demonstrated that the decreased CD3+CD4+ T cells (≤ 288cells/ul) were an independent risk of cardiac injury in DM patients with COVID-19 (adjusted OR, 2.501; 95% CI, 1.282–4.877; p = 0.007; Pinteraction = 0.018), but not in patients without DM." (PMID 36123740, 2022). "Moreover, several studies have reported that intensive care unit (ICU) patients have significantly fewer CD8+ T cells than CD4+ T cells, which appears to be associated with COVID-19-related disease severity and mortality." (PMID 36189203, 2022). "SARS-CoV-2 infected-patients develop specific antibodies, CD4+ T cells, and CD8+ T cells in response to the infection, although, CD4+ T cells had the strongest association with diminished COVID-19 disease severity compared with the other two arms (B cells, CD8+ T cells) of the adaptive immunity." (PMID 35844575, 2022). "As severe COVID-19 is associated with exacerbated inflammatory responses, IFNγ and IL-17 expression in S-specific CD4 T-cells were evaluated by PBMC stimulation with Peptivators, and evaluation of cytokine expression by intracellular flow cytometry within T-cells." (PMID 36139625, 2022). "(2021) identified a likely risk of developing prolonged symptoms of COVID-19 in hospitalized patients, noting that convalescent patients had a lower frequency of IL-10+ CD4+ T cells, IL-17+ CD4+ T cells, and IL-6+ B cells, compared to individuals with acute COVID-19." (PMID 35846757, 2022). "Notably, our data show that CD4+ T cell response is conserved to variants of concern both in recovered-COVID-19 subjects as well as in vaccinated individuals." (PMID 35154116, 2022). "This might be particularly relevant for PLWH with depleted CD4+ T cells, who appear to be at higher risk of severe COVID-19, and reduced responsiveness to vaccine." (PMID 36846557, 2022). "We also determined the profile of plasma cytokines and analyzed whether changes in plasma levels of ATP might be associated to the imbalance in the CD4+ T cell compartment observed in children with COVID-19." (PMID 35663467, 2022). "Thus, immune-inflammatory indicators, especially CD3+CD4+ T cells and IL-6, are recommended to distinguish the people who refer to a high risk of cardiac injury and mortality from COVID-19 patients with DM." (PMID 36123740, 2022). "Notably, compared with B and CD8+ T cells, the elevated levels of CD4+ T cells in acute COVID-19 had the strongest association with mild disease and rapid viral clearance." (PMID 35342348, 2022). "The COVID-19–associated CD4+ macrophages have morphologic characteristics of alveolar macrophages." (PMID 35446789, 2022).
COVID-19 (continued). "In particular, CD4+ T-cell clusters with the transcriptome features of high levels of endoplasmic reticulum (ER) stress and inflammation-related TFs were associated with severe COVID-19 patients with high level of FI." (PMID 35558069, 2022). "Neutrophil, immature granulocyte and CD4+ T-lymphocyte populations may be heavily implicated in the immunopathology of COVID-19." (PMID 35980979, 2022). "However, we still lack a complete understanding of how these abnormal CD4+ T cell profiles emerge in response to the paradoxical differentiation signals that characterize the cytokine storm associated with severe COVID-19." (PMID 36678366, 2022). "However persistant infection lead to further T cell exhaustion with lymphopenia with a high CD8+/CD4+ ratio as a major hallmark of progression to severe COVID-19." (PMID 35891232, 2022). "Consistent with the ability of CD4+ T cells to regulate the recruitment and function of phagocytes in peripheral tissues, severe COVID-19 in adults have shown to be associated with changes in the function of two different CD4+ T cell profiles; FoxP3+ regulatory T cells (Tregs) and TH17 cells." (PMID 35663467, 2022). "Also, monocytes from COVID-19 patients with severe disease downregulate HLA class II encoding genes and CD4 expression, which is associated with monocytes-to-macrophage differentiation and proinflammatory CD14 monocyte sub-population." (PMID 35284964, 2022). "Interestingly, a pronounced immunodeficiency (current CD4 count < 350/μL) was found to be associated with an increased risk for severe COVID-19 (aOR 2.85, 95% CI: 1.26–6.44, p = 0.01) and low nadir CD4 counts associated with an increased mortality." (PMID 35891555, 2022). "Notably, lower COVID-19 disease severity has been better associated with SARS-CoV-2 specific CD4+ T cells than CD8+ T cells and antibodies, whose main cytokine produced is IFN-γ." (PMID 36289890, 2022). "However, meta-regression showed that the association between HIV and mortality from COVID-19 was unaffected by age (p = 0.208), gender (p = 0.608), Black ethnicity (p = 0.389), CD4 cell count of <200 cells/μL (p = 0.353) or ART (p = 0.647)." (PMID 33936793, 2021). "In addition, the high IL-6 levels in COVID-19 patients were associated with a decrease in CD4+ and CD8+ T cells." (PMID 34123873, 2021). "The landscape indicates that a T-cell inflammatory state and a deficiency of CD4+ T cells in SCPs may contribute to the mechanisms underlying the pathogenesis of and recovery from COVID-19." (PMID 33717140, 2021). "For large CD4+ TCRbeta motifs, we show strong association with COVID-19 by analysing the occurrence patterns and frequencies of these sequences in a large cohort of COVID-19 patients." (PMID 33399535, 2021). "In a large multicentre, retrospective, cohort study involving 232 cancer patients and 519 patients without cancer, increased TNF-α and IL-6, as well as decreased lymphocytes and CD4+ T cells, were found to be risk factors for disease aggravation in patients with cancer and COVID-19." (PMID 34123873, 2021). "Several studies have shown that decreased CD4 T-cell and lymphocyte counts are associated with severe clinical types, which supports having weaker immune functions with T-cell exhaustion as contributing to the severity of COVID-19." (PMID 34646783, 2021). "COVID-19 is an interstitial pneumonia characterized by the lung accumulation of lymphocytes around pulmonary vessels associated with lymphocytopenia, predominating on CD4 and CD8 T-cells." (PMID 33557908, 2021). "Further, a CD4 count < 200 cells/μl during admission was associated with COVID-19 death." (PMID 32860699, 2021). "In addition, recent approaches have shown that the specific repertoire of SARS-CoV-2-reactive CD4 + T cells and Trm17 cells in the lungs has been associated with severe COVID-19 hyperinflammation." (PMID 34064728, 2021).